WASF3 (WASP family member 3)
Diseases named in the same sentence as WASF3 in open-access papers (continued):
Sharing a sentence is not in itself a finding about the gene and the disease.
ovarian carcinoma (2 papers, 2017 to 2024). A malignant neoplasm originating from the surface ovarian epithelium. "WASF3 has been shown to be associated with invasion in several cancers, including breast and ovarian cancer, and is inversely correlated with overall progression-free survival." (PMID 38857306, 2024).
pancreatic cancer (2 papers, 2023). "In various types of human cancer, such as colon, prostate, and pancreatic cancer, WASF3 is upregulated." (PMID 37176055, 2023). "In pancreatic cancer, the overexpression of WASF3 could promote the proliferation, migration and invasion of cancer cells by regulating the AKT pathway." (PMID 37322027, 2023).
bladder cancer (1 paper, 2017). "As proof of concept, Jin and co-workers have recently shown that knockdown of HSP70 led to reduction of matrix metalloproteinase 9 (MMP9) mRNA expression and WASF3/Wave3 protein levels in bladder cancer (BC) cell line." (PMID 29311994, 2017).
endometriosis (1 paper, 2026). The growth of functional endometrial tissue in anatomic sites outside the uterine body. "In hESC cells co-cultured with gestational epithelial endometriosis organoids, SFRP1, CDC42, RAC1, and WASF3 were upregulated, while PTK2B was downregulated, reflecting the miRNA cargo of ENDO-GEST-derived EVs." (PMID 42282918, 2026).
influenza (1 paper, 2017). An acute viral infection of the respiratory tract, occurring in isolated cases, in epidemics, or in pandemics; it is caused by serologically different strains of viruses (influenzaviruses) designated A, B, and C, has a 3-day incubation period, and usually lasts for 3 to 10 days. "Next, various deletion mutants of ATAD3A and WASF3 were generated and tagged with C-terminal sequences of c-myc and human influenza hemagglutinin protein, respectively." (PMID 29100377, 2017).
lung carcinoma (1 paper, 2014). "A significant correlation between the expression levels of WASF3 and the stage of lung cancer was observed in the present study." (PMID 25120680, 2014).
metastatic cancers (1 paper, 2021). A carcinoma which has spread from the original site of growth to another anatomic site. "In the future, refining stapled peptides inhibitors to interrupt WASF3-dependent immunocomplex or identifying novel WASF3 transcript inhibitors using genome-editing tools would facilitate the development of more effective therapeutics to improve clinical outcomes in metastatic cancers." (PMID 33467681, 2021).
myalgic encephalomyelitis (1 paper, 2023). "A recent report sheds light on the involvement of Wiskott–Aldrich Syndrome Protein Family Member 3 (WASF3) expression with the complex pathophysiology of myalgic encephalomyelitis/chronic fatigue syndrome (ME/CFS), and its influence on endoplasmic reticulum (ER), OS, and mitochondrial dysfunction." (PMID 38248493, 2023).
Peri-Implantitis (1 paper, 2019). An inflammatory process with loss of supporting bone in the tissues surrounding functioning DENTAL IMPLANTS. "Three common leader genes; PSMD10, SOS1, and WASF3, were identified from the gene clusters linked to peri-implantitis and T2DM each." (PMID 31275749, 2019). "Three leader genes (PSMD10, SOS1, WASF3), eight cross-talk genes (PSMD10, PSMD6, EIF2S1, GSTP1, DNAJC3, SEC61A1, MAPT, and NME1), and one signaling pathway (IL-17 signaling) emerged as peri-implantitis and T2DM linkage mechanisms." (PMID 31275749, 2019). "In addition, actin binding was found as a significantly dysregulated process by a whole-exome sequencing study of peri-implantitis, but no experimental study has yet characterized WASF3’s expression in peri-implantitis." (PMID 31275749, 2019).
squamous cell carcinoma (1 paper, 2014). A carcinoma arising from squamous epithelial cells. "The expression of WASF3 was significantly higher in adenocarcinoma compared with that in squamous cell carcinoma (P=0.010)." (PMID 25120680, 2014).
Xeroderma pigmentosum complementation group A (1 paper, 2019). Xeroderma pigmentosum complementation group A (XPA) is a severe form of xeroderma pigmentosum (XP; see this term), a rare photodermatosis predisposing to skin cancers. "These eQTLs are significantly associated with 4 genes, including ADGRB2 (adhesion G protein-coupled receptor B2), WASF3 (WAS protein family member 3), SPEF2 (sperm flagellar 2), and XPA (xeroderma pigmentosum complementation group A)." (PMID 31039743, 2019).
cancer (36 papers, 2012 to 2026). A tumor composed of atypical neoplastic, often pleomorphic cells that invade other tissues. "WASF3, a Wiskott-Aldrich syndrome protein family member, has been implicated in multiple studies as a regulator of the actin cytoskeleton and in cancer invasion, which is again consistent with our results." (PMID 38857306, 2024). "The overexpression of the WASF3 gene has been linked to several cancer-promoting activities, including increased cell proliferation and migration, as well as resistance to chemotherapy." (PMID 38125536, 2023). "WASF3 is a gene that encodes for the Wiskott-Aldrich syndrome protein family member 3, which is known to play a role in cancer development and progression." (PMID 38125536, 2023). "In this review, we focus our attention on the role of WASF3 in cancer metastasis by dissecting its underlying signaling network and molecular regulations." (PMID 33467681, 2021). "STAT3 has been consistently implicated in promoting cancer cell invasion and metastasis in many cancer types and was shown here to bind to its cognate elements in the WASF3 promoter." (PMID 34465361, 2021). "The WASF3 gene has been shown to be a promoter of cell invasion in vitro and metastasis in vivo in different cancer cell types." (PMID 38625593, 2025). "Knocking out the NCKAP1 gene markedly suppresses the migratory ability of cancer cells, likely due to a disruption of the WASF3 complex (WASF3 requires NCKAP1 to facilitate invasion and metastasis)." (PMID 38739940, 2024). "In conclusion, hsa-circ-0100153 has been found to be a potential biomarker for cancer diagnosis and prognosis, and WASF3 has been identified as a potential therapeutic target for cancer treatment." (PMID 38125536, 2023). "More research is needed to gain a better understanding of the WASF3 gene's role in cancer and to develop targeted therapies that can effectively inhibit its activity in cancer cells." (PMID 38125536, 2023). "The results of gene expression analysis in healthy and cancer patients, as well as the survival analysis, show that an increase in the expression of the WASF3 gene is visible in cancer patients, leading to lower survival rates." (PMID 38125536, 2023). "Despite the growing body of evidence pointing to the importance of the WASF3 gene in cancer, the exact mechanism by which it contributes to cancer development and progression is still not completely understood." (PMID 38125536, 2023). "ATAD3A and GRP78 together stabilize WASF3 at the mitochondrial membrane, promoting cancer metastasis." (PMID 37569886, 2023). "The analysis of the circRNA-miRNA-mRNA regulatory network revealed interactions between hsa-circ-0100153, hsa-miR-31, hsa-miR-767-3p, and hsa-miR-935 with WASF3 in cancer." (PMID 38125536, 2023). "WASF3 regulates the dynamics of the actin cytoskeleton, and it involved in the invasion and metastasis of cancer cells." (PMID 37322027, 2023). "In this study, we used a bioinformatics approach to identify additional functional pathways of the WASF3 gene and highlight its role in the regulation of circRNAs and miRNAs in cancer progression." (PMID 38125536, 2023). "This review focuses on the critical and distinct contributions of WASF3 in the regulation of signal pathways promoting cancer cell invasion and metastasis." (PMID 33467681, 2021). "Taken together, these findings contribute to the basis of our understanding of HSP70’s importance in WASF3 stabilization and, in turn, WASF3-mediated cancer cell invasion and metastasis." (PMID 33467681, 2021). "In one study, it was found that miRNA-200 levels were inversely correlated with WASF3 levels in cancer cells and that miRNA-200b inhibits WASF3 expression by directly targeting the 3′- untranslated regions (UTR) of WASF3 mRNA." (PMID 33467681, 2021). "The results showed that the expression of TAOK1, CMTM6 and CNOT7 were significantly lower in the adjacent cancers, while the expression of WASF3 was significantly higher in the adjacent cancers." (PMID 34336682, 2021).
cancer (continued). "Recently, ATAD3A has been the subject of intense interrogation for its role throughout cancer progression and, more specifically, its role in regulating WASF3 facilitated metastasis." (PMID 33467681, 2021). "Historically, the invasive influence of WASF3 has been studied through manipulating its expression in cancer cells in vitro and then engrafting these cells into models, like mice and zebrafish, to track metastasis." (PMID 33467681, 2021). "WAVE3 (WASF3), an adaptor and actin cytoskeleton remodeling protein, contributes to cell migration, cancer cell invasion, and metastasis." (PMID 33594155, 2021). "In another study, pharmacological inhibition of PI3K isoforms was similarly found to decrease cell motility, as well as suppress WASF3 induction in TLR5/7-treated ovarian SK-OV-3 cancer cells." (PMID 33467681, 2021). "We and others have demonstrated that WASF3 is a master regulator of the metastasis-related phenotypes previously assigned to other proteins and that inactivating it is sufficient to suppress cancer invasion and metastasis." (PMID 33467681, 2021). "In fact, our studies have shown that WASF3-mediated cancer invasion is contingent upon the HER2/HER3 heterodimer, which facilitates WASF3 phosphoactivation and transcription." (PMID 33467681, 2021). "Conceivably, SLPI seemingly accelerates the ability of cancer cells to migrate by upregulating genes associated with the organization of the actin cytoskeleton, including WASF1 and WASF3." (PMID 33016205, 2020). "WASF3 (WAS protein family member 3) controls actin binding, thus regulating cell shape and motility, and has been frequently implicated in cancer cell motility and metastasis." (PMID 31275749, 2019). "In cancer cells, HSP70 and HSP90 have been found to be essential for WASF3 metastasis-promoting protein stability, which contributes to cancer cell migration and invasion." (PMID 26863132, 2016). "The results demonstrated that the mRNA expression level of WASF3 in cancer tissues was markedly (approximately five times) higher compared with that of the normal tissues." (PMID 25120680, 2014). "Wiskott-Aldrich syndrome protein family member 3 (WASF3) is required for invasion and metastasis in different cancer cell types, and has been demonstrated to possess prognostic value in various types of human cancer." (PMID 25120680, 2014). "Mechanistic and clinical studies have clearly demonstrated WASF3 as a critical component in cancer progression and metastasis." (PMID 25120680, 2014). "We have previously shown that WASF3 is high expressed in primary human cancer and fundamentally important for metastatic spread of cancer cells." (PMID 24089705, 2013). "On the other hand, this study have shown that hsa-circ-0100153 is upregulated in cancer and may play a role in cancer progression by regulating the expression of WASF3 protein." (PMID 38125536, 2023). "The results of present research using bioinformatics tools suggest the existence of a regulatory mechanism between the WASF3 gene, circular RNA hsa-circ-0100153, and miRNAs (hsa-miR-31, hsa-miR-767-3p, and hsa-miR-935) that appears to affect the intensity of cancer invasion." (PMID 38125536, 2023). "Moreover, the regulatory effect of CYFIP1 on WASF3, knockdown in highly invasive cancer cells will lead to inhibition of invasion." (PMID 37206976, 2023). "In cancer cells, a high expression of WASF3 correlates with more aggressive tumors." (PMID 37176055, 2023). "The exact mechanisms by which ATAD3A promotes cancer metastasis are not fully understood, but it is thought to be related to its regulation of mitochondrial metabolism and dynamics, as well as its interaction with WASF3-dependent metastatic cascade involved in cancer progression." (PMID 37077859, 2023). "Some studies suggest that WASF3 may regulate the activity of other genes involved in cell growth and division, or interact with proteins that are important for cancer development." (PMID 38125536, 2023).
cancer (continued). "WASF3, a Wiskott–Aldrich syndrome protein family member, appears to play a major role not only in the regulation of actin cytoskeleton dynamics but also in cancer cell invasion/metastasis." (PMID 33467681, 2021). "The possible mechanism behind this observation is that inhibition of VEGF may target the angiogenic ability of cancer cells and create a hypoxic environment that, in turn, increases WASF3 levels." (PMID 33467681, 2021). "Consequently, the advent and potential employment of the Wasf3 deficient strain represent a new and promising opportunity to explore WASF3’s influence in cancer metastasis." (PMID 33467681, 2021). "Previous studies identified that Wiskott-Aldrich syndrome protein family 3 (WASF3; also termed, WAVE3), is critical for the regulation of actin cytoskeleton dynamics via the activation of the Arp2/3 complex, and is involved in cancer cell motility, invasion and metastasis." (PMID 25120680, 2014). "WASF3, as a member of the Wiskott–Aldrich syndrome protein/WAVE family of structurally and functionally associated proteins, is significant in the regulation of actin polymerization in the cytoskeleton, cell motility and cancer cell invasion." (PMID 25120680, 2014). "The data from the present study indicates that WASF3 may present as a useful biomarker for cancer progression and metastasis." (PMID 25120680, 2014). "For example, the p38 mitogen-activated protein kinase (MAPK) signaling pathways, which are activated by WASF3, may possess a selective advantage in several types of cancer." (PMID 25120680, 2014). "Therefore, it was reasonable to hypothesize that missense mutations of SASH1 and WASF3 might cause target gene mutations of anticancer drugs in LUAD, thereby causing drug resistance in cancer cells." (PMID 37322027, 2023). "Furthermore, WASF3 contributed to cancer cells proliferation, migration and invasion." (PMID 31426562, 2019). "Aside, these findings are similar to those surrounding miR-218 whose expression suppresses cancer cell migration and EMT and directly targets WASF3." (PMID 33467681, 2021). "Additionally, WASF3 has been hypothesized to be involved in cancer invasion in numerous cancer cell lines, which implies that WASF3 may be critical in cancer progression and metastasis." (PMID 25120680, 2014). "Knockdown of NCKAP1 in cancer cells suppressed WASF3 protein levels but not WASF3 transcript levels." (PMID 33467681, 2021). "Finally, invasion and metastasis were also evaluated in vitro and in vivo using MCF7 cells and mice and were found to be significantly enhanced following the co-expression of WASF3 and HER2, further demonstrating the crucial role of HER2-WASF3 in cancer metastasis." (PMID 33467681, 2021). "Interestingly, restoration of WASF3 expression in MDA-MB-231 cells did not alleviate the suppressive effect of SHOX2 loss on tumor outgrowth, as evidenced by similar primary tumor sizes and Ki67-positive cancer cell numbers." (PMID 34465361, 2021). "Accordingly, heat shock experiments across various cancer cell lines further resulted in increased levels of HSP70 and WASF3 protein without an increase in WASF3 mRNA." (PMID 33467681, 2021).
tumor (29 papers, 2010 to 2025). "WASF3 was uniquely noted to be reproducibly decreased upon LINC03045 KD, as well as associated with decreased tumor cell invasion upon WASF3 KD." (PMID 38857306, 2024). "RNAseq analysis of LINC03045 knockdown revealed that WASF3, previously implicated in tumor invasion studies, was highly correlated with lncRNA expression, while WASF3 KD was associated with significant decrease in invasion." (PMID 38857306, 2024). "As a result of the univariate analysis, the tumor staging (P=0.005) and WASF3 expression (P=0.006) were identified to be associated with overall survival." (PMID 25120680, 2014). "Additionally, the GO term for cytoskeleton organization (GO: 0007010) process was enriched for WASF3, which is consistent with prior literature that describes cytoskeletal reorganization as commonly associated with tumor invasion." (PMID 38857306, 2024). "Herein, targeting WASF3 at the levels of transcription, protein stability, and phosphorylation holds great promise for metastasis suppression, regardless of the diverse genetic backgrounds associated with tumor development." (PMID 33467681, 2021). "Because high-level knockdown (>90%, at the protein level) did not affect cell proliferation rates, we have described WASF3 as an invasion and metastasis promoter, although the in vivo studies clearly demonstrate that loss of WASF3 function also affects tumor development." (PMID 20717117, 2010). "Analysis of patient data, tumor cell lncRNA knockdown, and WASF3 knockdown reveal that WASF3 mediates the LINC03045 tumor effect." (PMID 38857306, 2024). "In prior literature, implicated overlapping genes, including WASF3, EDNRB, SOX10, BAMBI have been implicated in processes including tumor progression, migration, and invasion." (PMID 38857306, 2024). "Delineating the mechanisms by which WASF3 gain and activation promote tumor metastasis provides us a deeper understanding of the biology of tumor progression and the tailoring needed to improve treatment regimens." (PMID 33467681, 2021). "Whereas Wiskott Aldrich syndrome protein family member 3 (WASF3) is required for tumor invasion and metastasis." (PMID 34336682, 2021). "In the present study, the results of IHC and qPCR clearly demonstrate that WASF3 expression was increased in the tumor tissue samples, which indicates a potential role for the WASF3 protein in the pathogenesis of NSCLC." (PMID 25120680, 2014). "There was a significant correlation observed between WASF3 expression and the tumor stage (P=0.013)." (PMID 25120680, 2014). "In lungs from the mice receiving the WASF3-knockdown cells, only infrequent, small tumor foci were seen in the mice showing surface nodules." (PMID 20717117, 2010). "SHOX2 can also directly activate the tumor metastasis-related gene WASF3, recruit the signal transduction-related factor STAT3 at its promoter site, and form a molecular complex with STAT3, which collectively enhances the activity of WASF3, promoting tumor metastasis." (PMID 39289763, 2024). "Additionally, Wiskott–Aldrich syndrome family member 3 (WASF3), a protein necessary for tumor migration, invasion, and metastasis, was shown to be stabilized by HSP70 and HSP90 proteins." (PMID 37884988, 2023). "Furthermore, knockdown of WASF3 significantly reduced xenograft tumor growth and metastasis in vivo." (PMID 20717117, 2010). "Finally, gene expression analysis following LINC03045 KD revealed that WASF3, a factor evaluated for tumor cell invasion in multiple studies, could be a possible mediator of LINC03045 function." (PMID 38857306, 2024). "In the luminal A subtype, the variation in mRNA levels and overexpression of the VEGF, PDGF, ANG1, PF4, WASF3, and TPM3 genes coincided in both types of samples (platelets and tumor tissue, respectively)." (PMID 37176055, 2023). "DOCK11 showed significantly lower levels in tumor datasets, while MCAM, MYO10, and WASF3 exhibited significantly higher levels in tumor datasets, compared with the normal group." (PMID 34128858, 2021).